SIX3-AS1 (SIX3 antisense RNA 1)
Synonyms: SIX3OS
Gene: Long non-coding RNA gene on chromosome 2 (44,940,130 to 44,945,785, reverse strand). Ensembl gene ENSG00000236502.
Gene Ontology:
Biological process: regulation of gene expression